ZNF763 (zinc finger protein 763)
Description:
May be involved in transcriptional regulation.
Synonyms: ZNF440L; ZNF
Tractability: PROTAC: ubiquitination databases record sites on it.
Gene: Protein-coding gene on chromosome 19 (11,965,037 to 11,980,617, forward strand). Ensembl gene ENSG00000197054.
Subcellular location: Nucleus
Subcellular location (Human Protein Atlas): Nucleoplasm
Gene Ontology:
Molecular function: protein binding; DNA-binding transcription factor activity; RNA polymerase II cis-regulatory region sequence-specific DNA binding; sequence-specific double-stranded DNA binding
Biological process: regulation of transcription by RNA polymerase II; regulation of DNA-templated transcription
Cellular component: nucleus
Genetic constraint (gnomAD): Loss-of-function variants: 33 observed, 39.5 expected, observed/expected ratio (o/e) 0.84, 90% interval 0.63 to 1.12. The upper end of that interval is the gene's LOEUF score, 1.12, which puts it in group 4 of 6, group 1 being the genes least tolerant of losing a copy. Missense variants: 423 observed, 491.59 expected, observed/expected ratio (o/e) 0.86, 90% interval 0.79 to 0.93. Synonymous variants: 155 observed, 167.98 expected, observed/expected ratio (o/e) 0.92, 90% interval 0.81 to 1.05.
Homologues: Orthologues: mouse Zfp78 (32% identical), Drosophila melanogaster CG3281 (23% identical), Drosophila melanogaster CG2712 (21% identical), Drosophila melanogaster Phs (19% identical). Paralogues in human: ZNF439 (78% identical), ZNF69 (78% identical), ZNF440 (77% identical), ZNF20 (57% identical), ZNF491 (51% identical), ZNF555 (44% identical), ZNF124 (40% identical), ZNF77 (40% identical), ZFP90 (39% identical), ZNF266 (38% identical), ZNF599 (38% identical), ZNF404 (38% identical), and 50 more.
Diseases named in the same sentence as ZNF763 in open-access papers:
ZNF763 is named in the same sentence as 3 diseases in open-access papers, as found by Europe PMC text mining. Sharing a sentence is not in itself a finding about the gene and the disease. The quoted sentences say what the papers report.
cervical cancer (1 paper, 2021). A primary or metastatic malignant neoplasm involving the cervix. "ZNF763 is a typical zinc finger protein containing Krüppel-associated box (KRAB), which is reportedly related to the development of cervical cancer." (PMID 34464378, 2021). "Taken together, it is suggested that ZNF763 may contribute to the occurrence of cervical cancer by enhancing NF-κB signaling and changing cell growth." (PMID 34464378, 2021).
herpes simplex infection (1 paper, 2021). "Our study identified DE TFs such as ZNF180, ZNF763, ZNF792, ZNF718, and ZNF461 associated with asthmatic ASM cells and enriched for the herpes simplex infection pathway." (PMID 34257337, 2021).
ZNF763 also shares sentences with these, for which no sentence is quoted: cancer (2 papers).